FABP4 (fatty acid binding protein 4)
Diseases named in the same sentence as FABP4 in open-access papers (continued):
Sharing a sentence is not in itself a finding about the gene and the disease.
tumor (continued). "Compared with those in the normal pancreas (GTEx + TCGA), CA9, TNNT1, CCL21, LY86, and CCL19 were all expressed higher in tumor tissues, except for FABP4, which was expressed lower in a tumor (p < 0.001)." (PMID 34777388, 2021). "We also observed that macrophages with NF‐κB inhibition promoted the proliferation and migration of SK‐N‐SH cells, and blunted the tumor‐inhibiting effects of FABP4‐knockdown macrophages." (PMID 33931964, 2021). "In our study, we demonstrated that IL1α stimulated by FABP4 knockdown takes the main responsibility of macrophages phenotype skewing and anti‐tumor ability." (PMID 33931964, 2021). "In mice, 6 weeks of spontaneous PA before liposarcoma injection and 8 weeks of voluntary wheel running post-tumor injection increased IL-6, FABP4, PPAR-γ, autophagy markers, and tumor growth." (PMID 33670492, 2021). "We then focused on the cytokines secreted by CMs of FABP4‐knockdown macrophages, which exerted anti‐tumor ability through inhibiting NB cell proliferation and migration." (PMID 33931964, 2021). "In vivo bioluminescence imaging demonstrated that FABP4 overexpressed macrophages significantly expanded the metastatic tumor size, while FABP4 suppression diminished the metastatic tumor size." (PMID 33931964, 2021). "We found that the mRNA expression levels of FABP3 or FABP4 were related to different tumor stages of CRC." (PMID 34680577, 2021). "The univariate analysis revealed that the prognosis of patients with GIST was related to FABP4 expression (p < 0.001), tumor size (p = 0.026), mitotic index (p = 0.027), and AFIP‐Miettinen risk levels (p < 0.001)." (PMID 34558731, 2021). "This put FABP4 at the heart of a communication between adipocytes and tumor stimulating MMPs and cytokine production in the PCa stromal microenvironment to favor tumor progression." (PMID 34354670, 2021). "The data showed that FABP4 expression correlated with the increase in tumor size (p = 0.002), mitotic index (p < 0.001), and AFIP‐Miettinen risk stratification (p = 0.001)." (PMID 34558731, 2021). "Both pro-tumorigenic and anti-tumorigenic roles have been ascribed to FABP4 according to tumor type and TME." (PMID 34386430, 2021). "Previous studies proved that FABP4 expression levels were inconsistent in different tumor tissues and played different roles." (PMID 34558731, 2021). "FABP4 synthesis in the adipocytes seems to be a critical step for fatty acid transfer from adipocytes to cancer cells, and has a role in angiogenesis and tumor proliferation." (PMID 34440886, 2021). "The expression of FABP4 is higher in metastatic ovarian cancer than in primary tumors, and it has been proposed as a tumor marker for metastatic disease." (PMID 34440886, 2021). "Haung and coworkers also uncovered FABP4-mediated tumor/TME crosstalk that sustains PCa invasive potential." (PMID 34386430, 2021). "CAPG, together with ANXA5 and FABP4, was previously found within a group of biomarkers differentiating invasive from noninvasive MM rat tumor models, their abundance being very significantly increased and decreased, respectively." (PMID 32867073, 2020). "Bone marrow adipocytes are able to promote tumor growth in bone via a FABP4-dependent mechanism through induction of interleukin-1β and oxidative interaction between the FABP4 and PPAR-γ pathways." (PMID 31492897, 2020). "Lipids can also be trafficked between bone marrow adipocytes and cancer cells by upregulation of FABP4 and fuel growth and invasiveness in metastatic tumor cells." (PMID 33339340, 2020). "FABP4 is also expressed at a higher level in cancer cells, and its upregulation promotes tumor growth." (PMID 33083529, 2020). "Fatty acid transport between tumor cells and adipocytes and its metabolism are complex systems, in which FABP4 plays a vital role." (PMID 33088219, 2020). "A negative correlation was observed in bladder cancer patients that showed a decrease in FABP4 transcript with histologic grade and tumor progression." (PMID 32856199, 2020).
tumor (continued). "BMS309403, a small molecule inhibitor of FABP4, was used and the results showed that it not only significantly reduced tumor burden in a syngeneic orthotopic mouse model but also increased the sensitivity of cancer cells towards carboplatin." (PMID 33194756, 2020). "Inhibition of FABP4 reduced metastatic tumor burden in vivo, and also increased the sensitivity of OvCa cells toward carboplatin when treated with a small-molecule inhibitor of FABP4 (BMS309403)." (PMID 33233362, 2020). "Among these genes, PLP2 was upregulated and positively associated poorer survival, whereas LYVE1, FABP4, TGFBR3, and FXYD6 were downregulated and identified as tumor suppressor genes." (PMID 31803141, 2019). "To assess the potential anti-tumoral effect of FABP4 in vivo, we measured tumor growth in two experimental HFD mice model xenografted (heterotopic and orthotopic) with HepG2 cells." (PMID 30575815, 2019). "The tumor suppressor effect of FABP4 in PTC and its molecular mechanisms deserve further investigation." (PMID 31803141, 2019). "The fatty acids are transferred to AML blasts via FABP4, which help to promote tumour cell proliferation." (PMID 31334678, 2019). "The involvement of FABP4 in human carcinogenesis is a subject of debate, and results differ depending on tumor type." (PMID 30575815, 2019). "In conclusion, our study confirms the oncogenic role of FABP4 in liver carcinogenesis, highlighting the key role of tumor microenvironment via crosstalks between endothelial and tumors cells mainly through microvesicles release from endothelial cells." (PMID 30575815, 2019). "Nevertheless, recent studies showed that adipocytes surrounding tumor cells provide energy by supplying fatty acids to cancer cells through FABP4." (PMID 30575815, 2019). "In accordance with the results of our study, FABP4 was identified as a tumor suppressor in multiple cancers." (PMID 31803141, 2019). "The expression of FABP4 was found in ovarian cancer and acute myeloid leukemia at the adipocyte-tumor cell margin, providing fatty acids for rapid tumor growth." (PMID 31500658, 2019). "Metabolomics experiments found higher unsaturation and oxidation of fatty acid species in high FABP4-expressing human tumor specimens, and these metabolic abnormalities were correlated with poor overall and progression-free survival." (PMID 31769430, 2019). "Surprisingly, double immunostaining showed that FABP4 expression in human HCC was mainly restricted to tumor cell-lining endothelial cells." (PMID 30575815, 2019). "Direct transfer of lipids between adipocytes and OC cells was shown to be mediated by FABP4, which was highly upregulated in metastatic versus primary tumor sites." (PMID 31769430, 2019). "The tumor weight of FABP4 overexpression was smaller and lighter than those generated by control cells (n = 4, P = 0.0238)." (PMID 29733540, 2018). "The mice that received FABP4 siRNA had a significant decrease in aggregate tumor weight (80%, p < 0.01) as well as number of metastatic nodules (75%, p < 0.01) compared with control mice." (PMID 30050129, 2018). "Using DESI-MSI, we compared tumor tissues of FABP4 siRNA group (low FABP4 expression, n = 3) to control siRNA samples (high FABP4 expression, n = 3)." (PMID 30050129, 2018). "All patients were divided into two groups according to IHC staining intensity (H‐score) of FABP4 in tumor tissues." (PMID 29733540, 2018). "The tumor metastasis rate with FABP4 overexpression was significantly higher at sites such as the diaphragm, liver, and pelvis, whereas tumors in the control mice were mainly observed at the site of injection (ovary) and in the mesentery." (PMID 30050129, 2018). "Treatment with DOPC nanoliposomes containing either miR-409-3p mimic or FABP4 siRNA inhibited tumor progression in mouse models." (PMID 30050129, 2018). "From those results, several metabolites were specifically expressed in either low or high FABP4 expressing patient tumor samples." (PMID 30050129, 2018).
tumor (continued). "Similar to the previous experiment, FABP4 siRNA treatment resulted in significant reduction in tumor weight (p < 0.05) and the number of nodules (p < 0.05)." (PMID 30050129, 2018). "Expression of FABP4 was examined in the tumor sections using immunohistochemistry, and expression of FABP4 was higher in sections from the ectopic FABP4 group than in those from the control group." (PMID 30050129, 2018). "Compared with the control mice, mice injected with cells ectopically expressing FABP4 had a significantly higher tumor burden (~3-fold, p < 0.01), as well as an increased number of distant metastatic nodules (~3-fold, p < 0.01)." (PMID 30050129, 2018). "We found that FABP4 was lowly expressed in HCC tissues compared to the corresponding tissue adjacent, and the expression of FABP4 was significantly associated with the tumor size, PVTT, recurrence‐free survival and overall survival." (PMID 29733540, 2018). "It suggested that FABP4 inhibited tumor grow of HCC cells in vivo, and these results were consistent with the inhibited growth of HCC cells by FABP4 in vitro." (PMID 29733540, 2018). "Our preclinical studies show that ectopic expression of FABP4 increases tumor progression while in vivo experiments with DOPC nanoliposomes show that silencing FABP4 reduces the extent of metastasis." (PMID 30050129, 2018). "To identify the effects of the tumor microenvironment on FABP4 expression, we next examined various factors, including co-cultures with fibroblasts, macrophages, mesothelial cells and hypoxia treatment." (PMID 30050129, 2018). "We found that FABP4 was mainly expressed in cytoplasm, and the tumor tissues showed weaker staining when compared to the paired normal tissues, which was consistent with the results of real‐time PCR and Western blot." (PMID 29733540, 2018). "FABP4 is known to be upregulated in many aggressive cancers as well as recurrent tumours to facilitate the uptake and transport of extracellular FA from adipocytes to mitochondria for β-oxidation." (PMID 30510774, 2018). "The antitumor properties of miR-409-3p stem from its inhibitory effects on FABP4, as shown by the fact that restoration of FABP4 rescued the tumor suppressive effects of miR-409-3p on cancer cells." (PMID 30050129, 2018). "Therapeutic delivery of siRNA led to reduced endothelial FABP4 expression and significant reduction of tumour growth." (PMID 27568980, 2017). "Vascular FABP4 expression in the stroma of the primary tumour was also significantly higher than in the stroma of omental metastasis." (PMID 27568980, 2017). "This shows that tumour endothelial FABP4 expression is induced by activation of NOTCH1 signalling, and can be targeted by inhibition of VEGFA and NOTCH1 signalling." (PMID 27568980, 2017). "In fact, FABP4 expression is increased in tumor cells cocultivated with adipocytes in vitro and in human tumors that invade AT." (PMID 28915700, 2017). "This, in addition to effects of FABP4 on FA metabolism and mitochondrial ROS in ECs in vitro, strongly supports a role of FABP4 in tumour angiogenesis." (PMID 27568980, 2017). "The expression of FABP4 in vessels of the fat tissue distant from the tumour was significantly higher than in vessels directly adjacent to tumour cells." (PMID 27568980, 2017). "In omental metastasis, we observed similar FABP4 expression in the vessels of the stroma, the tumour–stroma interface and the tumour–fat interface." (PMID 27568980, 2017). "In vivo, we found that increased NOTCH1 signalling in tumour xenografts led to increased expression of endothelial FABP4 that decreased when NOTCH1 and VEGFA inhibitors were used in combination." (PMID 27568980, 2017). "Here, we investigated the role of FABP4 in endothelial fatty acid metabolism and tumour angiogenesis." (PMID 27568980, 2017). "We observed a significant inhibition of tumour growth with mouse FABP4 KD; a <70% reduction of tumour weight and number of tumour nodules with both siRNA treatments." (PMID 27568980, 2017).
tumor (continued). "The aim of this study was to delineate the role of FABP4 in the progression of PCa with a focus on its interaction with the stromal cell tumor microenvironment." (PMID 29340091, 2017). "Our data show that FABP4 is required for angiogenesis and an important target in tumour angiogenesis, especially in tumours that are low grade, rich in stroma and embedded in FA-rich tissues." (PMID 27568980, 2017). "Through therapeutic delivery of siRNA targeting mouse FABP4, we investigated the effect of endothelial FABP4 knockdown on tumour growth and blood vessel formation." (PMID 27568980, 2017). "In these xenografts, we found that more than 50% of the vessels in DLL4-overexpressing xenografts showed a strong FABP4 expression compared with 10–20% of the vessels in the control (empty vector, EV) tumours (P<0.00001)." (PMID 27568980, 2017). "We next tested two compounds with potential to affect adipocyte–tumor cell interactions: a selective inhibitor of fatty acid-binding protein 4 (FABP4) (BMS309403), and Atglistatin, a selective inhibitor of Adipocyte Triglyceride LIpase (ATGL)." (PMID 27458427, 2016). "Given the known role of FABP4 in lipid transport and hydrolysis, its apparent induction by the inhibitors of lipolysis suggests a potential feedback response by tumor cells overwhelmed with adipocyte-supplied lipids." (PMID 27588494, 2016). "Podgorski and colleagues demonstrated that lipids can be trafficked between adipocytes and cancer cells fuelling tumour growth and invasiveness by upregulating FABP4, IL-1β and HMOX-1 in the metastatic tumour cells." (PMID 27761371, 2016). "Despite potent inhibition of PC3 invasion in 2D, only modest inhibition of tumor invasion was observed with FABP4 inhibitor in a 3D assay, a result potentially due to differences in matrix and experimental conditions between the two assays." (PMID 27458427, 2016). "This provides additional evidence that body fat content and FABP4 (as key substrates and enzymes of fat metabolism) functioned synergistically when fueling rapid tumour growth and metastasis." (PMID 26959740, 2016). "We have shown previously that FABP4 levels are significantly induced in tumor cells exposed to adipocyte-derived factors." (PMID 27588494, 2016). "FABP4 regulates inflammatory pathways in adipocytes and macrophages and is involved in both inflammatory diseases and tumor formation." (PMID 24732569, 2014). "Beyond its high in vivo stability, [125I]TAP1 also had preferable biodistribution in normal mice, and moderate tumor accumulation that partly corresponded to the FABP4 in vivo expression profile." (PMID 24732569, 2014). "Here, we provided specific evidence for accumulation of marrow fat cell-supplied lipids by tumor cells, and demonstrated that the accelerated growth and invasiveness involves upregulation of tumor-derived FABP4, IL-1β and HMOX-1." (PMID 24240026, 2013). "In the present study, exposure of tumor cells to adipocyte-derived factors led to PPARγ-driven FABP4 upregulation followed by PPARγ downregulation." (PMID 24240026, 2013). "To determine if PPARγ is also involved in FABP4 overexpression in tumor cells exposed to adipocyte-derived factors, we treated tumor cells with either PPARγ agonist rosiglitazone (ROSI) or with Adipo CM in the absence or presence of PPARγ antagonist GW9662." (PMID 24240026, 2013). "Collectively, our data demonstrate that metastatic tumor cells utilize marrow adipocyte-supplied lipids to thrive and progress in skeletal sites and suggest a functional role for FABP4 abundance in the bone metastatic niche." (PMID 24240026, 2013). "This suggests that FABP‐4 could contribute to tumor progression from the early stages through to metastasis." (PMID 40857027, 2026). "Our findings generate a testable hypothesis regarding FABP4's role in balancing anti-tumor immunity and stromal promotion." (PMID 42193082, 2026).
tumor (continued). "In the field of tumor therapy, small-molecule inhibitors targeting FABP4 (such as BMS-309403) can inhibit tumor angiogenesis and epithelial-mesenchymal transition (EMT), and their synergistic effects with chemotherapeutic drugs have entered preclinical research stages." (PMID 40717587, 2025). "FABP4 normally facilitates fatty acid transport and storage, and its downregulation may signify a broader shift in tumor cell energetics." (PMID 40870889, 2025). "After treatment for 17 days, 1,200 μg of the anti-FABP4 mAb effectively suppressed tumor growth." (PMID 41392988, 2025). "To test this hypothesis, we used immunostaining to examine the protein expression of key factors involved in fatty acid uptake and metabolism, including CD36 and FABP4, in tumor tissues." (PMID 40526430, 2025). "Furthermore, FABP4 can modulate inflammatory pathways crucial for tumor survival and proliferation under stress." (PMID 39823981, 2025). "FABP4 promotes tumor cell proliferation and EMT through the PPARγ/β-catenin axis." (PMID 40717587, 2025). "This FABP4/UCP2 axis was enriched in adipocyte-rich tumour microenvironments and correlated with increased stemness and mesenchymal traits in persisted cells, which could be reversed by the FABP4 inhibitor BMS309403." (PMID 41149452, 2025). "FABP4 may exert its tumour-suppressive effects by downregulating Snail and phosphorylated STAT3 (p-STAT3), inhibiting the epithelial-mesenchymal transition (EMT) and oncogenic STAT3 signalling." (PMID 41149452, 2025). "Genetic ablation of FABP4 delays the onset of tumor development in a MASLD-HCC mouse model." (PMID 41392988, 2025). "In the context of cancer, FABP4 is crucial in driving tumour proliferation, metastasis, and drug resistance by activating oncogenic signalling pathways and modulating cellular metabolism to meet energy demands, highlighting its potential as a therapeutic target in cancer treatment." (PMID 41149452, 2025). "Furthermore, the neutralizing effect of the anti-FABP4 mAb on rhFABP4-induced tumor incidence rate and tumor growth was also evidenced in PLC/PRF/5 cells when these cells were cotreated with 100 ng/mL rhFABP4 prior to subcutaneous injection into nude mice." (PMID 41392988, 2025). "Targeting adipocyte-derived FABP4 may offer a new treatment approach, blocking cancer stem cell-driven tumor growth." (PMID 41392988, 2025). "However, some tumor cells, particularly those near to adipose tissue, exhibited positive staining for FABP4." (PMID 40106183, 2025). "Notably, our study does suggest that FABP4 possibly induces inflammatory changes in the tumor microenvironment by affecting the crosstalk between cancer cells and surrounding stromal cells." (PMID 41226657, 2025). "Consistent with our hypothesis, we observed impaired tumor growth in Fabp4–/– mice, as evidenced by a significant decrease in liver mass and the number of tumor nodules." (PMID 41392988, 2025). "Furthermore, BMAT enhances tumor growth in bones through the FABP4 pathway, which also promotes adipogenesis in a reciprocal manner." (PMID 40852589, 2025). "Additionally, treatment with BMS309403—a chemical inhibitor of FABP4—was observed to abrogate the HF-mediated TRAMP tumor progression, along with reductions in body weight and cytokine production." (PMID 41226657, 2025). "In addition, in tumor cells overall expression of FABP5 (47.2 ± 60.46) was significantly higher than that of FABP4 (8.49 ± 18.24)." (PMID 40106183, 2025). "Since tumor cells mainly spread through the lymphatic and vascular systems, FABP4 may mediate adipose/tumor crosstalk by enhancing tumor invasion." (PMID 40106183, 2025). "EMT in tumor cells was correspondingly attenuated after FABP4 expression was suppressed." (PMID 39984452, 2025). "Functional roles are context-dependent, for instance, CRABP2 may act as either tumour suppressor or promoter, and FABP4 exhibits metabolic state dependent effects." (PMID 41149452, 2025).